RNY1P6 (RNY1 pseudogene 6)
Gene: Miscellaneous RNA gene on chromosome 13 (51,586,424 to 51,586,532, reverse strand). Ensembl gene ENSG00000206920.
Homologues: Orthologues: chimpanzee Y_RNA (98% identical), macaque Y_RNA (94% identical). Paralogues in human: Y_RNA (84% identical), RNY1P5 (83% identical), Y_RNA (83% identical), Y_RNA (82% identical), Y_RNA (81% identical), Y_RNA (80% identical), Y_RNA (79% identical), RNY1P14 (78% identical), Y_RNA (78% identical), RNY1 (77% identical), RNY1P1 (77% identical), Y_RNA (77% identical), and 94 more.